GCC2 (GRIP and coiled-coil domain containing 2)
Description:
Golgin which probably tethers transport vesicles to the trans-Golgi network (TGN) and regulates vesicular transport between the endosomes and the Golgi. As a RAB9A effector it is involved in recycling of the mannose 6-phosphate receptor from the late endosomes to the TGN. May also play a role in transport between the recycling endosomes and the Golgi. Required for maintenance of the Golgi structure, it is involved in the biogenesis of noncentrosomal, Golgi-associated microtubules through recruitment of CLASP1 and CLASP2.
Synonyms: GCC185; RanBP2L4; KIAA0336; REN53
Tractability: Small molecule: a structure with a bound ligand is known. Antibody: UniProt places it where antibodies can reach, with medium confidence. PROTAC: ubiquitination databases record sites on it; its protein half-life has been measured.
Gene: Protein-coding gene on chromosome 2 (108,449,107 to 108,509,415, forward strand). Ensembl gene ENSG00000135968.
Subcellular location: Cytoplasm; Golgi apparatus, trans-Golgi network membrane
Subcellular location (Human Protein Atlas): Golgi apparatus; Nucleoplasm
Pathways (Reactome):
Disease: Signaling by ALK fusions and activated point mutants
Vesicle-mediated transport: Retrograde transport at the Trans-Golgi-Network
Gene Ontology:
Molecular function: identical protein binding; protein binding; small GTPase binding
Biological process: Golgi ribbon formation; Golgi to plasma membrane protein transport; late endosome to Golgi transport; microtubule anchoring; microtubule organizing center organization; protein localization to Golgi apparatus; protein targeting to lysosome; recycling endosome to Golgi transport; retrograde transport, endosome to Golgi
Cellular component: Golgi apparatus; membrane; nucleoplasm; trans-Golgi network; cytosol; cytoplasm
Genetic constraint (gnomAD): Loss-of-function variants: 58 observed, 115.23 expected, observed/expected ratio (o/e) 0.5, 90% interval 0.41 to 0.63. The upper end of that interval is the gene's LOEUF score, 0.63, which puts it in group 2 of 6, group 1 being the genes least tolerant of losing a copy. Missense variants: 1,165 observed, 1,155.8 expected, observed/expected ratio (o/e) 1.01, 90% interval 0.96 to 1.06. Synonymous variants: 424 observed, 414.99 expected, observed/expected ratio (o/e) 1.02, 90% interval 0.94 to 1.11.
Homologues: Orthologues: macaque GCC2 (97% identical), rabbit GCC2 (86% identical), chimpanzee GCC2 (84% identical), dog GCC2 (81% identical), pig GCC2 (81% identical), mouse Gcc2 (78% identical), rat Gcc2 (77% identical), tropical clawed frog gcc2 (54% identical), Drosophila melanogaster GCC185 (17% identical). Paralogues in human: NUMA1 (17% identical), GOLGA3 (14% identical), CEP164 (11% identical).
Diseases named in the same sentence as GCC2 in open-access papers:
GCC2 is named in the same sentence as 21 diseases in open-access papers, as found by Europe PMC text mining. Sharing a sentence is not in itself a finding about the gene and the disease. The quoted sentences say what the papers report.
lung carcinoma (4 papers, 2019 to 2025). "Subsequently, a receiver operating characteristic (ROC) curve was constructed to assess the diagnostic value of the exosomal GCC2 protein for patients with early-stage lung cancer." (PMID 34771645, 2021). "We also evaluated the diagnostic capacity of the exosomal GCC2 protein in patients with early-stage lung cancer." (PMID 34771645, 2021). "High expression levels of GCC2 in the peripheral blood of patients demonstrate both specificity and sensitivity for early-stage lung cancer." (PMID 40575159, 2025). "Among structural proteins, cytoskeletal proteins (such as TPM3 and GCC2) have been detected in lung cancer exosomes." (PMID 35158999, 2022). "Although GCC2 is expressed in most cancer cell types, it exhibits relatively moderate cytoplasmic and membranous immunoreactivity in most cancers, including lung cancer." (PMID 34771645, 2021). "GCC2 in peripheral blood exosomes for diagnosis is expected to greatly contribute to the detection of asymptomatic early-stage lung cancer patients during routine screening." (PMID 34771645, 2021). "GCC2 is located on the exosome membrane; therefore, detecting GCC2+ exosomes using an antibody is easy, making it possible to diagnose lung cancer by analyzing the GCC2 exosome biomarker in the peripheral blood of the patients in the future." (PMID 34771645, 2021). "Results revealed that the GCC2 protein concentrations were significantly higher (normal 9.07 pg/mL vs. patients’ 26.28 pg/mL, p < 0.001) in early-stage lung cancer patients (T1aN0-T1bN0; n = 30) than in the normal controls (n = 16)." (PMID 34771645, 2021). "Next, we quantified the exosomal GCC2 protein levels in early-stage lung cancer patients’ plasmas using ELISA." (PMID 34771645, 2021). "The newly proposed biomarker GCC2 was identified through proteomic analysis of exosomes secreted from lung cancer cell lines." (PMID 34771645, 2021). "Surprisingly, the GCC2 protein levels in patients with early-stage lung cancer (T1aN0-T1bN0) increased by more than 3.2-fold (p < 0.0001) compared with those of the normal group." (PMID 34771645, 2021). "GCC2 expression was very weak in the normal group; however, it gradually increased as the pathological stage of lung cancer progressed." (PMID 34771645, 2021). "Compared to that in the normal group, the GCC2 protein level increased progressively in the patients as the pathological stages of lung cancer progressed, indicating that GCC2+ exosomes could be a reliable biomarker to detect NSCLC." (PMID 34771645, 2021). "Collectively, these results indicated that the presence of GCC2 on the surface of the exosomes could be a predictive marker for lung cancer diagnosis, suggesting that GCC2 could be a potential biomarker for NSCLC." (PMID 34771645, 2021). "This suggests that GCC2 expression is likely to be upregulated in specific lung cancer cell types." (PMID 34771645, 2021). "In order to examine whether GCC2 could be used as a potential biomarker for lung cancer, we tested the RNA and protein expression levels in the different cell lines." (PMID 34771645, 2021). "The non‐small cell lung cancer harboring GCC2‐ALK fusion gene supports the hypothesis that the GCC2‐PDGFRB gene products could behave as an oncoprotein." (PMID 30697976, 2019). "However, in three patients with lung cancer, the GCC2 gene was shown to fuse with anaplastic lymphoma kinase (ALK; MIM #105590), which has a critical role in the pathogenesis of non‐small cell lung cancer, and targeting it with crizotinib was shown to be active against cancer." (PMID 30697976, 2019). "Therefore, exosomal GCC2 protein expression could distinguish early stage patients from healthy individuals, thus suggesting that exosomal GCC2 could be used for the early diagnosis of lung cancer." (PMID 35158999, 2022). "TUBA1C, GAPDH, KRT25, GCC2, and POTEKP were the five proteins identified as potential lung cancer-specific exosome biomarkers." (PMID 34771645, 2021).
lung carcinoma (continued). "Notably, the GCC2 levels were significantly high in patients with early-stage (T1aN0-T1bN0) lung cancer, which suggests that plasma-derived exosomal GCC2 protein level could be a feasible, valuable, and non-invasive biomarker for the early diagnosis of lung cancer." (PMID 34771645, 2021).
Autoimmunity (2 papers, 2022 to 2023). The occurrence of an immune reaction against the organism's own cells or tissues. "A recent report identified increased autoimmunity in global GCC2–/– (knockout) mice with development of autoantibodies against a wide range of antigens." (PMID 37676733, 2023).
breast carcinoma (1 paper, 2020). "In TCGA breast cancer samples, only reduced expression of GCC2 and ASH1L could show poor RFS." (PMID 33363011, 2020).
Hirsutism (1 paper, 2018). Abnormally increased hair growth referring to a male pattern of body hair (androgenic hair). "In addition to validation of SNPs associated with these previous traits, our study identified three novel hirsutism loci that were also eQTLs for BCL2, GCC2 and LIMS1, and TBX15." (PMID 29895819, 2018).
melanoma (1 paper, 2022). A malignant, usually aggressive tumor composed of atypical, neoplastic melanocytes. "We first generated Sec24c, Gcc2, Rab14 and Npc1 pooled CRISPR-KO B16 melanoma cells and implanted them in C57BL/6 wild-type mice." (PMID 36379959, 2022).
metastasis (1 paper, 2025). The spread or migration of cancer cells from one part of the body (where they first appeared) to another. "A 66-year-old man with IMT bone metastasis accompanied by GCC2-ALK fusion and another man with pulmonary IMT underwent postoperative disease progression with STRN-ALK fusion both obtained PR following treatment with ensartinib." (PMID 40386559, 2025).
osteosarcoma (1 paper, 2025). A usually aggressive malignant bone-forming mesenchymal neoplasm, predominantly affecting adolescents and young adults. "To evaluate the impact of GCC2-directed LG convergence in a setting more relevant to a human solid tumor, we performed similar experiments using human osteosarcoma cell lines, including the highly resistant LM7 and the relatively resistant 143B tumor cells." (PMID 39813120, 2025). "When triggering 721.221 target cells were added, however, the killing of osteosarcoma cells was detectable, but only by the GCC2 KO cells." (PMID 39813120, 2025). "In experiments using either the YTS parental or GCC2 KO cells, these cells could be seen in close approximation with a 721.221 target cell and osteosarcoma cells." (PMID 39813120, 2025). "Thus, LG dispersion owing to the absence of GCC2 was associated with increased bystander cell killing after triggering even when these bystander cells were otherwise resistant human osteosarcoma cells." (PMID 39813120, 2025).
ovarian dysfunction (1 paper, 2024). The inability of the ovaries to function. "tRF-1:30-Gly-GCC-2 may be a novel molecular target for improving the development of atretic follicles in ovarian dysfunction." (PMID 39201747, 2024).
skin cutaneous melanoma (1 paper, 2015). "Surprisingly, four of the genes containing RRA missense mutaions in Uveal Melanoma (DCC, CR1, GCC2 and CLCN1) were predicted as diver genes in TCGA skin cutaneous melanoma dataset." (PMID 25903059, 2015).
cancer (6 papers, 2010 to 2022). A tumor composed of atypical neoplastic, often pleomorphic cells that invade other tissues. "Gcc2-deleted or Rab14-deleted cancer cells induce T-cell and IFN-dependent anti-tumour immunity and inhibit tumour growth in mice." (PMID 36379959, 2022). "We identified an exosomal protein, GCC2, through proteomic analysis of exosomal proteins extracted from five cancer cell lines." (PMID 34771645, 2021). "The qRT-PCR analysis revealed that expression levels of the GCC2 gene in H1299 and H522 were fourfold higher than in HPAEpiC and the other cancer cell lines." (PMID 34771645, 2021). "Interestingly, the GCC2 protein levels in exosomes isolated from cancer cell lines and patient plasma at different NSCLC pathological stages were dramatically higher than those of the respective controls." (PMID 34771645, 2021). "Next, to examine whether the GCC2 protein is expressed in the cancer cell line-derived exosomes, we analyzed GCC2 protein levels in the exosomal lysates of H1299, H522, and HPAEpiC cells." (PMID 34771645, 2021). "Some of them were commonly investigated in cancer, while others were rarely reported, such as GCC2 and LINC00189, which may hold significant role in regulating specific module networks." (PMID 27602771, 2016). "Some of them are cancer related, such as POU2F3, NKD1 and CYP2C8, while LINC00189, GCC2 and OR9Q1 genes are rarely reported in human diseases." (PMID 27602771, 2016). "In this study, we report on the use of GCC2 as a specific biomarker to distinguish between cancer-specific exosomes and normal cell-derived exosomes isolated from the body fluids of NSCLC patients, which can improve the diagnosis of cancer." (PMID 34771645, 2021).
tumor (4 papers, 2022 to 2025). "In the xenograft mouse model, GCC2 knockdown H460 cells formed smaller tumours than controls; hence, GCC2 promoted tumour growth." (PMID 40293576, 2025). "GCC2 promoted tumour growth by modulating vesicle trafficking of EGFR to the nucleus." (PMID 40293576, 2025). "This suggests that GCC2 regulates LG convergence to promote efficiency against a triggering target cell and prevents killing of neighboring cells in a simulated three-dimensional tumor microenvironment setting." (PMID 39813120, 2025). "GCC2 knockdown reduced vesicle trafficking of EGFR to the nucleus and tumour proliferation." (PMID 40293576, 2025).
genetic disease (1 paper, 2025). "In this context and through extension to a new human genetic disease, Golgi-GCC2 linkages demonstrate a mechanism for preventing bystander killing while promoting killing efficiency that is required for human host defense." (PMID 39813120, 2025).
GCC2 also shares sentences with these, for which no sentence is quoted: chronic eosinophilic leukemia (1 paper); colon cancer (1); large intestine cancer (1); leprosy (1); liver cancer (1); neurological disease (1); non-small cell lung carcinoma (1); prostate carcinoma (1); uveal melanoma (1).